ERAP1 (endoplasmic reticulum aminopeptidase 1)
Diseases named in the same sentence as ERAP1 in open-access papers (continued):
Sharing a sentence is not in itself a finding about the gene and the disease.
Hypertension (continued). "However, to date, no systematic, prospective epidemiological data are available that examine the relevance of the ERAP1 and ERAP2 gene loci as risk markers for hypertension." (PMID 29850473, 2018). "Furthermore, genetic–molecular approaches have identified variants among ERAP1 and ERAP2 genes that are associated with preeclampsia, hemolytic uremia, and hypertension." (PMID 29850473, 2018). "Therefore, the lower placental zinc concentration may also contribute to the dysfunction of the ERp44/ERAP1 complex, further exacerbating the hypertension in PE." (PMID 36848863, 2023). "In this context, given the role of ERAP enzymes in the regulation of RAS, hypertension, antigen processing, inflammatory disorders, and cytokines and NO release, we hypothesize that knowledge of ERAP1 and ERAP2 genotypes may be useful in identifying the appropriate therapy for each COVID-19 patient." (PMID 33567739, 2021). "Therefore, we speculate that in PE, the higher ERp44 forms a complex with ERAP1, preventing the secretion and cleavage of Ang II, which would otherwise promote hypertension." (PMID 32210971, 2020). "We thus posit that disordered ERAP1 levels may contribute to the pathophysiology of hypertension." (PMID 29850473, 2018). "Defective variants of ERAPs (i.e., low activity ERAP1 allotypes and lack of functional ERAP2) exacerbate the impact of SARS-CoV-2 on hypertension and organ damage." (PMID 35769458, 2022). "In conclusion, the present findings provide evidence for the involvement of ERAP1 and ERAP2 gene loci in blood pressure regulation and the pathogenesis of hypertension with an added indication of ERAP1 gene locus as a potential therapeutic target for blood pressure management." (PMID 29850473, 2018).
spondyloarthritis (8 papers, 2016 to 2025). "It shares some features of a spondyloarthropathy, based on the association with HLA-B51, epistatic endoplasmic reticulum aminopeptidase 1 (ERAP-1) interactions, increased T helper (Th) 17 response, and neutrophilic involvement." (PMID 34768694, 2021). "This fact was suitably stated by Robert and colleagues some years ago in the context of the association of ERAP1 with AS: “Determining how ERAP1 influences the development of spondyloarthritis may be as complicated as deciphering the role of HLA-B27”." (PMID 30425713, 2018). "Many B*27+ patients with spondyloarthritis also have functionally abnormal ERAP1 variants, which are uncommon in healthy donors; whether this affects MHCI protein turnover generally, or B27 turnover specifically, in these patients is an interesting question for future research." (PMID 27529174, 2016).
type 1 diabetes (8 papers, 2011 to 2025). "The ERAP1 variant, rs30187, is a non-synonymous SNP, K528R, located in exon 6 of the gene previously associated with AS, with Ps and PsA (personal communication, Anne Barton), and also with type 1 diabetes." (PMID 21281511, 2011). "In type I diabetes, ERAP1 was found to be regulated by the IRE1a/miR-17-5p axis, thus suggesting its involvement in β-cell destruction." (PMID 32824160, 2020). "Another candidate of interest for follow-up investigations is ERAP1, which encodes the endoplasmic reticulum aminopeptidase 1 and is involved in MHC class I antigen processing, hence immune processes, as well as in peptide catabolic processes and type 1 diabetes." (PMID 35953519, 2024).
inflammatory bowel disease (7 papers, 2018 to 2025). A spectrum of small and large bowel inflammatory diseases of unknown etiology. "Further mechanistic studies are warranted to elucidate how ERAP1 modulates disease progression and to identify novel ERAP1-related therapeutic targets for the treatment of inflammatory bowel disease." (PMID 40977735, 2025). "We assess the burden of functionally impactful variants present in ERAP1 and ERAP2 in 2 cohorts of patients diagnosed with inflammatory bowel disease (IBD; Crohn’s disease (CD) or ulcerative colitis (UC))." (PMID 41428259, 2025).
preeclampsia (7 papers, 2014 to 2025). Preeclampsia is a hypertensive disorder of pregnancy that is characterized by new-onset hypertension with proteinuria presenting after 20 weeks of gestation, and depending on mild or severe forms may initially present with severe headache, visual disturbances, and hyperreflexia. "The present study confirmed a genetic association between ERAP2 and preeclampsia, and, for the first time, reported an association between ERAP1 and eclampsia." (PMID 33762660, 2021). "Endoplasmic reticulum aminopeptidases 1 and 2 (ERAP1 and 2) are involved in blood pressure regulation and single nucleotide polymorphisms (SNPs) of these genes have been linked to preeclampsia." (PMID 31223582, 2019). "There was also evidence of a genetic association with preeclampsia for the endoplasmatic reticulum aminopeptidases 1 and 2 (ERAP1 and 2) genes." (PMID 24991435, 2014). "The STOX1 gene, the ERAP1 and 2 genes, the syncytin envelope gene, and the −670 Fas receptor polymorphisms are involved in the development of preeclampsia." (PMID 24991435, 2014). "In conclusion, we identified genetic variants in ERAP1 and ERAP2 associated with eclampsia and preeclampsia, respectively." (PMID 33762660, 2021). "This study attempted to disclose the possible implications of the ERAP1 and ERAP2 gene polymorphisms in predisposing the pregnant women to preeclampsia using Real-Time allelic discrimination Taq-Man assays." (PMID 31223582, 2019). "Ongoing investigation resulted differently from before performed studies considering the role of ERAP1 and ERAP2 gene polymorphisms in predisposing women to preeclampsia, emphasizing on the genetic structure differences among various racial populations." (PMID 31223582, 2019). "Large-scale family studies have identified associations between preeclampsia and genetic variations in ACVR2 (activin A receptor type 2A), ROCK2 (coiled-coil-containing protein kinase 2), ERAP1 (endoplasmic reticulum aminopeptidase 1), and ERAP2 (endoplasmic reticulum aminopeptidase 2)." (PMID 40507612, 2025). "In conclusion, ERAP1 gene is associated with eclampsia whereas ERAP2 is associated with preeclampsia, although the mechanism by which genetic variants in ERAPs influence the risk of preeclampsia and eclampsia remain to be elucidated." (PMID 33762660, 2021). "Last but not least, it is important to study further to gain more insight into the role of ERAP1 and 2 genes in the pathogenesis of preeclampsia; nevertheless, either determination of miscellaneous indices alongside with genetic analysis and investigation of various populations would be beneficial." (PMID 31223582, 2019). "The genotype C/C, in ERAP1 rs30187 variant (c.1583 T > C, p.Lys528Arg), was associated with increased risk of eclampsia (OR = 1.85, p = 0.019) whereas ERAP2 haplotype rs2549796(C)–rs2927609(C)–rs11135484(G) was associated with preeclampsia (OR = 1.96, corrected p-value = 0.01)." (PMID 33762660, 2021). "Even though the comprehensive understanding of ERAP2 lags that of ERAP1 due to the lack of an animal model, recent studies have shown that both enzymes are associated with an increased risk of several diseases, including pregnancy disorder pre-eclampsia (PE), recurrent miscarriages, and cancer." (PMID 36834865, 2023). "Finally, we investigated the presence of variants in four selected genes previously reported in relation to preeclampsia; the ROCK2, ACVR2A, ERAP1, and ERAP2 genes." (PMID 29758065, 2018). "Predicted deleterious variants in ROCK2, AVCR2A, ERAP1, and ERAP2 in women with (cases) and without (controls) preeclampsia." (PMID 29758065, 2018).
uveitis (7 papers, 2013 to 2025). An inflammatory process affecting a part of or the entire uvea. "Genes associated with the risk of developing uveitis include ERAP1, intergenic region 2p15, IL23R, IL10-IL19, IL18R1-IL1R1, IL6R, KIF21B, and EYS." (PMID 35629038, 2022). "Among the ERAP1 polymorphisms associated with the risk of uveitis are rs2032890, rs27529, rs30187, and rs2287987 (the relationship is greater for the rs2287987/-rs10044354 haplotype)." (PMID 35629038, 2022). "A missense mutation in ERAP1 p.Asp725Gln showed susceptibility in patients with BD uveitis only under HLA-B*51 positivity, and ERAP1 susceptibility was abolished in HLA-B*51-negative patients." (PMID 33912164, 2021). "Genome-wide association tests were performed in the subgroup of GWAS discovery collections with BD uveitis and two SNPs in ERAP1 were identified to confer risk for BD uveitis recessively—rs10050860 and rs17482078, which encode p.Asp575Asn and p.Arg725Gln alterations in ERAP1 respectively." (PMID 37841268, 2023). "Levels of cluster C12 proteins were generally lower in the serum of patients compared with that of control participants (e.g., interferon β1), whereas proteins of cluster C13 often showed uveitis subtype-specific expression patterns (e.g., endoplasmic reticulum aminopeptidase 1 in anterior uveitis)." (PMID 36245752, 2022). "In our study, we did not confirm the relationship between ERAP1 rs2287987 and the occurrence of uveitis but rather with enthesitis." (PMID 35629038, 2022). "The ERAP1 rs2287987 AA genotype was more frequently observed in patients with enthesitis (AA vs. G+, p = 0.049), while the TNFRSF1B rs1061622 GG genotype was more common in participants with uveitis (GG vs. TT, p = 0.042)." (PMID 35629038, 2022). "The ERAP1 rs2287987 GG genotype was more frequently observed in patients with enthesitis, while the TNFRSF1B rs1061622 GG genotype was more common in participants with uveitis than the TT genotype." (PMID 35629038, 2022).
COVID-19 (6 papers, 2021 to 2023). A disease caused by infection with severe acute respiratory syndrome coronavirus 2. "It is therefore likely important to include the ERAP1 allotypic state in genetic analyses that focus on HtLA associations with predisposition to severe COVID-19." (PMID 34688668, 2021). "Our findings suggest that ERAP1 allotypes can be a major contributor to heterogeneity in antigen presentation, and in conjunction with HLA-allele binding specificity, contribute to variable immune responses to disease including COVID-19." (PMID 34688668, 2021). "The stratification according to age showed a statistically significant difference in the stimulated mRNA levels only for ERAP1 (adolescent COVID-19 patients vs. controls, ANOVA Tukey post hoc test, p adjusted <0.05)." (PMID 37047752, 2023). "The univariate and multivariate logistic regression analysis showed that age, male gender, non-vaccination, ACErs4291A, and ERAP1 rs26618T alleles are independent risk factors for severe COVID-19." (PMID 36673116, 2023). "The existence and potential role of ERAP1 allotypes have only recently been recognized and thus have not been studied in the context of COVID-19 susceptibility." (PMID 34688668, 2021). "In contrast, adult COVID-19 patients with MIS-A have been associated with autophagy genes (LGALS8, TECPR1), viral restriction factor genes (PLIN3, EXOSC5, RNASE2), and immune responses (ERAP1, SIGLEC15, GAB2, GOLGA4, SNX3) in addition to Kawasaki disease genes (PEAR1, ERAP1)." (PMID 36430629, 2022). "Our results, however, suggest that ERAP1 allotypic variation could play, in tandem to HLA alleles, important roles in determining anti-SARS-CoV-2 immune responses and by extension, susceptibility to severe COVID-19." (PMID 34688668, 2021). "Moreover, the ERAP1 rs26618 TT genotype was markedly increased in the severe COVID-19 group (50%) versus 12.5% in the mild COVID-19 group (p < 0.001) and 26.3% in the non-infected controls (p = 0.0006)." (PMID 36673116, 2023).
colorectal cancer (5 papers, 2020 to 2025). A primary or metastatic malignant neoplasm that affects the colon or rectum. "Among these, 28 genes were previously associated with colitis or colorectal cancer, of which 11 were upregulated and 17 downregulated in ERAP1+/- mice." (PMID 40977735, 2025). "Transcriptomic analysis identified 428 differentially expressed genes between ERAP1+/− and WT colons, among which 28 were associated with colitis or colorectal cancer." (PMID 40977735, 2025). "The treatment interaction analysis for certain SNPs such as for ERAP1 and CIITA showed interaction with oxaliplatin, which has been shown to cause immunogenic cell death in colorectal cancer cells and upregulate MHC class I via the nuclear factor-kappa B (NF-κB) pathway." (PMID 40141198, 2025). "Transcriptomic analysis via RNA sequencing revealed upregulation of genes implicated in colitis and colorectal cancer (CRC) progression, such as Anxa9, Atp2a1, and Hepacam2, in ERAP1+/− mice, regardless of sulfasalazine administration." (PMID 40977735, 2025).
endometrial carcinoma (4 papers, 2012 to 2025). A malignant tumor arising from the epithelium that lines the cavity of the uterine body. "The effect of ERAP1 on angiotensin II modulates angiogenesis and therefore leads to the occurrence of endometrial carcinoma." (PMID 34395615, 2021). "The differential expression of ERAP1 and ERAP2 has been associated with several cancer types, including thyroid, lung, breast, colon, and endometrial cancers." (PMID 28977897, 2017). "The authors also showed that ERAP1 suppresses angiogenesis and endothelial cell migration in human endometrial carcinoma by regulating the angiotensin II concentration." (PMID 22942706, 2012). "Expression of ERAP1 has been detected in 64% of endometrial carcinomas and correlated with CA-125 levels, suggesting a role of this enzyme in endometrial cancer cell growth and differentiation." (PMID 22942706, 2012). "Moreover, in animal studies, ERAP1-overexpression by endometrial carcinoma cells leads to a reduction in both VEGF immunoreactivity and the number of blood vessels within tumors, implicating ERAP1 in the modulation of endothelial cell migration and VEGF-induced angiogenesis." (PMID 40226591, 2025).
influenza (4 papers, 2023 to 2025). An acute viral infection of the respiratory tract, occurring in isolated cases, in epidemics, or in pandemics; it is caused by serologically different strains of viruses (influenzaviruses) designated A, B, and C, has a 3-day incubation period, and usually lasts for 3 to 10 days. "Note that a common SNV in the ERAP1 gene also confers differential susceptibility to influenza infection, suggestive of similar pathogen-driven selection on the ERAP1 gene." (PMID 37925533, 2023).
lung carcinoma (4 papers, 2014 to 2023). "Global test for association of all ERAP1 polymorphisms with lung cancer gives χdf=102=32.6,p=0.000314 It is worth noting that this association can be discovered in the Caucasian population only after taking into account information about smoking history." (PMID 34149699, 2021). "In the present study, we demonstrated a significantly lower level of ERAP1 mRNA expression in lung cancer tissue compared to adjacent normal tissue." (PMID 37101107, 2023). "ERAP1 was lost in all tested breast, ovary, and lung carcinomas and in 6 out of 7 liver carcinoma samples tested, whereas ERAP2 was retained only in 9 out of 26 samples." (PMID 25566501, 2014). "Our results are novel, as no study on ERAP1 polymorphism in lung cancer has been published so far." (PMID 28083613, 2016). "No other populations have been tested so far for ERAP1 polymorphisms in lung cancer." (PMID 28083613, 2016). "Our study revealed significantly lower expression of ERAP1 mRNA in lung cancer tissue compared to adjacent non-tumor tissue obtained from the same patients." (PMID 37101107, 2023). "Remarkably, in four types of carcinomas (breast, ovary, liver, and lung carcinomas) arising from normal counterparts co-expressing ERAP1 and ERAP2, none of the 26 tested samples retained this phenotype." (PMID 25566501, 2014).
T-cell lymphoma (4 papers, 2012 to 2021). "Studies in syngeneic mice indicate rejection of T-cell lymphoma RMA following the inhibition of ERAP1 through a tumor-specific NK cell response due to impaired pMHC class I engagement of Ly49C/I NK cell-inhibitory receptors." (PMID 34745129, 2021). "To evaluate the relevance of the ER peptide trimming inhibition on tumorigenicity, we stably reduced ERAP1 expression in a murine T-cell lymphoma by ERAP1-targeted small interfering RNA." (PMID 22942706, 2012).
Arthritis (3 papers, 2018 to 2024). Inflammation of a joint. "The association of ERAP1 rs30187 with clinical phenotypes is well investigated in AS, a type of arthritis affecting the joints in the spine." (PMID 30514861, 2018). "Eliminating ERAP1 expression mitigates HLA-B27 misfolding and partially protects rats from the arthritis component of the SpA phenotype, while gut inflammation was exacerbated." (PMID 38811719, 2024). "We recently demonstrated that ERAP1-deficiency partially protects HLA-B27-Tg rats from developing arthritis but not gut inflammation." (PMID 38811719, 2024).
breast carcinoma (3 papers, 2019 to 2024). "This is in line with a study reporting that inhibition of ERAP1 sensitizes the transplantable 4T1 breast cancer cell model to anti-PD-1 immunotherapy." (PMID 39438988, 2024). "For example, synergism has been shown between peptide-presenting HLA-B and the peptidase ERAP1 in breast cancer." (PMID 33901204, 2021).